SOX10 (SRY-box transcription factor 10)
Diseases named in the same sentence as SOX10 in open-access papers (continued):
Sharing a sentence is not in itself a finding about the gene and the disease.
breast carcinoma (continued). "Expression of Sox9, Sox10 and Slug was seen in 82-96% of the tumor cells prior to chemotherapy in our study, further supporting the fact that the transcription factors are highly active in the breast cancer tissue." (PMID 24404438, 2013). "Sox10 was previously shown to be present also in breast cancer." (PMID 24404438, 2013). "Furthermore, identifying specific target genes, pathways and processes regulated by SOX10 in the context of breast cancer may provide a novel therapeutic approach in the treatment of TNBCs." (PMID 30279965, 2018). "Breast cancer suppressor candidate-1 (BCSC-1) could down-regulate MITF by binding to SOX10." (PMID 22912767, 2012). "SOX10 has been reported to show expression in approximately 40–70% of TNBC cases, making it a useful marker in identifying basal-like breast carcinomas." (PMID 39518009, 2024). "We then analyzed Sox10 expression in different subtypes of breast cancer, observing that similar to AMD1, Sox10 was remarkably elevated in BLBC in four gene expression datasets." (PMID 38654332, 2024). "SOX10 is primarily known for its role in melanocytic and neural crest-derived tumors but has gained recognition for its expression in TNBC and basal-like breast carcinomas." (PMID 39518009, 2024). "Currently, the transcription factor SRY box 10 (SOX-10) and the type 1 trichorhinophalangeal syndrome (TRPS-1), as markers of breast cancer diagnosis by IHC, have been included in TNBC diagnostic assays." (PMID 37686305, 2023). "Taken together, our data suggests that AR is expressed in many breast carcinomas, however unlike SOX10, it cannot be used as an independent biomarker." (PMID 30279965, 2018). "GATA3 and SOX10 are useful markers; however, they are not specific for breast cancer." (PMID 40025593, 2025). "Of note, GATA3, SOX10, and mammaglobin are not considered to be specific for breast carcinoma." (PMID 37306115, 2024). "The broader applicability of TRPS1 across breast cancer subtypes makes it a more robust marker in both routine and challenging cases, particularly in poorly differentiated tumors or TNBC, where SOX10 alone may not provide sufficient diagnostic clarity." (PMID 39518009, 2024). "SOX10 has found utility in identifying basal-like and metaplastic breast carcinomas, where other markers may not be expressed." (PMID 39518009, 2024). "Based on the results, we hypothesized that triple-negative breast cancer (TNBC) has a considerably greater SOX10 expression rate than other types of breast cancer." (PMID 36120242, 2022). "Furthermore, clustering 13 breast cancer cell lines with shRNA scores of MZF1, SOX10 and ZEB1, could roughly distinguish TNBC cell lines from nTNBC cell lines." (PMID 28423538, 2017). "Predicted regulatory element sequences for NANOG, CREB1, CPBP, BEN, PREB-1, SOX10, and POU2F1 (OCT1) POU6F1 and MEIS1 were highly enriched in the promoter regions of the tissue context dependent genes suggesting their possible roles in stem cells proliferation in HER2-regulated breast cancer tissue." (PMID 25428913, 2015). "Therefore, SOX10 is not considered a true breast cancer marker but may more likely indicate basal/myoepithelial differentiation in breast cancer." (PMID 40822238, 2025). "Gata binding protein 3 (GATA-3), SRY-Box transcription factor 10 (SOX-10), and estrogen receptor (ER) markers were negative, ruling out primary breast cancer." (PMID 37899461, 2023). "The FOXA1 gene, which opposes SOX10 expression, cooperates with ER1 to maintain luminal identity in breast cancer, whereas GATA3, XBP1, and CA12 showing a negative correlation with SOX10, also cooperate in ER1 signaling." (PMID 36496864, 2022).
glioma (39 papers, 2011 to 2026). A benign or malignant brain and spinal cord tumor that arises from glial cells (astrocytes, oligodendrocytes, ependymal cells). "Cluster analysis was performed, and SOX10 was identified as a distinguished biomarker to explore the prognostic value and association with the glioma immune microenvironment." (PMID 36524115, 2022). "More recently, SOX10 expression profiles in gliomas have been analysed, revealing its potential as a prognostic marker." (PMID 40159622, 2025). "Overall, boric acid treatment effectively downregulated the elevated SOX10 expression in glioma cells and robustly induced ferroptosis activation, resulting in a significant reduction in cell viability." (PMID 40159622, 2025). "In summary, our findings provide the first evidence of the relationship between SOX10 and ferroptosis in glioma cells." (PMID 40159622, 2025). "We demonstrate that boric acid modulates the SOX10/GPX4/ACSL4 axis, elucidating the involvement of SOX10 signalling in ferroptosis within glioma cells." (PMID 40159622, 2025). "Nearly all SOX genes, including SOX1, SOX2, SOX7, and SOX10, have been shown to influence glioma progression and exhibit oncogenic functions across multiple cancer types." (PMID 40159622, 2025). "Similar to control tumors, Ascl1-OE GFP+ tumor cells co-localized with either GFAP or SOX10, indicating a “mixed glioma” phenotype." (PMID 39609428, 2024). "By increasing Nestin, the oligodendroglial differentiation transcription factor SOX10, which was upregulated in gliomas, enhances the CSCs characteristic in breast cancer." (PMID 39170516, 2024). "Higher magnification images confirmed that tdTOM mostly colocalized with either GFAP or SOX10, indicating that they are “mixed gliomas” comprising of both astroglial or oligodendroglial lineages, respectively." (PMID 39609428, 2024). "CircEPHB4, as defined here, has not been investigated yet, but another circRNA from the same locus (hsa_circ_0081519) has been shown to positively regulate stemness and the proliferation of glioma cells by sponging miR-637 and up-regulating SOX10." (PMID 38203852, 2024). "The stemness and self-proliferation of glioma cells were promoted by circEPHB4 via sponging miR-637, which then released its inhibition on SOX10." (PMID 39170516, 2024). "The values of SOX2 across all steps suggest some stemness, either glioma stem cells or more likely tumor cells with stem cell phenotype considering low expression of SOX10 and NESTIN." (PMID 39230703, 2024). "TFBS for factors such as ZNF85, PO3F1, HX36, SOX1, and SOX10 were found in genes overexpressed in GII gliomas." (PMID 36850002, 2023). "Further, the transcriptional regulators MYRF/C11ORF9 and SOX10, which are essential for the initiation and maintenance of myelination, were under-expressed in PM gliomas." (PMID 37055795, 2023). "In terms of hRNA, all glioma cell lines showed a significant decrease in SOX10 expression (−4502; −26,634; −19,800), indicating that SOX10 is highly expressed in our normal human brain control." (PMID 36142793, 2022). "We performed multiplex immunofluorescence in the controlled group and different grades of glioma groups to further characterize the relationship between SOX10-expressed cells and neighboring CD68+CD163+ cells, and CD8+ cells." (PMID 36524115, 2022). "We are the first to evaluate the cluster ability thoroughly and other characteristics of the SOX family and analyze SOX10 expression profiles in gliomas in prognostic potential, immune response, and co-expression in single-cell sequencing." (PMID 36524115, 2022). "The results indicate that SOX10 regulates the types and quantity of glioma infiltrated immune cells." (PMID 36524115, 2022). "Sox10 is expressed widely in gliomas and promotes gliomagenesis triggered by platelet-derived growth factor-B." (PMID 34976314, 2022). "We performed a survival analysis of different SOX10 expressions in pan-glioma, LGG, and GBM based on TCGA and CGGA datasets." (PMID 36524115, 2022).
glioma (continued). "The Kaplan–Meier curves more securely demonstrated that grievous survival mischief in glioma patients with high SOX10." (PMID 36524115, 2022). "Almost all SOX genes, for instance, SOX1, SOX2, SOX7, and SOX10, have been found to have the potential to regulate the progression of glioma, whose expression levels are also related to the prognosis of patients." (PMID 36524115, 2022). "Considering that SRY mainly depends male sex, we identified SOX10 as a biomarker of glioma prognosis." (PMID 36524115, 2022). "In gliomas, Sox-10 is recognized as a marker of oligodendroglial differentiation, which is associated with increased survival." (PMID 36005160, 2022). "The transcription factors OLIG2 and SOX10 are expressed in all cells of the oligodendrocyte lineage, and these TFs exhibit broad expression across the glioma subtypes." (PMID 34976314, 2022). "The quantity of CD8+ cells at the distance of 0–25 μm and 25–50 μm neighboring SOX10-expressed cells exploded in the Glioma WHO IV group, while the amount of CD68+CD163+ cells also increased." (PMID 36524115, 2022). "In conclusion, our study demonstrates the outstanding cluster ability of the SOX family, indicating that SOX10 is an immune regulator of macrophage in gliomas, which can be an effective target for glioma immunotherapy." (PMID 36524115, 2022). "Concentrating on SOX10, multiple results imply that it has a multifaceted prognostic value in gliomas." (PMID 36524115, 2022). "Most of the gliomas categorized in the “SOX10 promoter hypomethylation” group consisted of DCGs, thalamic and brainstem gliomas in the “K27” group, and some of the cerebral gliomas in the “RTK I” group." (PMID 28852847, 2017). "nf1a+/−/nf1b−/− mutants in the p53zdf1/zdf1 background developed brain tumors in 33 weeks, with characteristic markers (sox10/Olig2/Gfap) of diffuse high-grade gliomas and hyperactivation of ERK and mTOR pathways, similar to mouse models and human gliomas." (PMID 28930163, 2017). "A paired overexpression of ErbB3 and Sox10 has been observed in pilocytic astrocytoma (PA) a common glioma of childhood, which verifies their network connection found in the current study." (PMID 23835063, 2013). "The lifetime hazard estimate decreased with increased levels of Sox10 in Caucasian individuals (HR = 0.55) compared to non-Caucasian individuals, and this pattern is concordant with broad distribution of Sox10 in high grade gliomas." (PMID 21649900, 2011). "In contrast, COL4A2 and SOX10 appear to act as tumor suppressors in glioma pathophysiology." (PMID 41727650, 2026). "Moreover, this study is the first to establish a link between SOX10 overexpression in glioma cells and its involvement in ferroptosis signalling, specifically through the GPX4/ACSL4 axis in U87 cells." (PMID 40159622, 2025). "Furthermore, SOX10 has emerged as a potential predictor of immunotherapy response and immune effector activity, underscoring its relevance in glioma treatment strategies." (PMID 40159622, 2025). "SOX10 (SRY-box transcription factor 10) is overly expressed in glioma." (PMID 38790260, 2024). "Further studies also observed SOX10 expression in other tumors including clear cell sarcoma, granular cell tumors, salivary gland tumors with myoepithelial differentiation, gastrointestinal stromal tumors, and gliomas." (PMID 38813332, 2024). "Moreover, the Ku80+ cells in these LGGs also expressed CD133 and ABCG1, markers of glioma stem cells, but were immunonegative for SOX10 and p16 expression, which can be observed in some patient pediatric LGGs." (PMID 35986378, 2022). "In our study, the high expression of SOX10 is related to shorter OS in glioma." (PMID 36524115, 2022). "Given that, SOX10 has the potential to be an auspicious target for glioma immunotherapy." (PMID 36524115, 2022). "The results revealed that SOX10 expression is elevated with the increase in glioma grades." (PMID 36524115, 2022).
glioma (continued). "In gliomas, SOX10 overexpression corresponds to immune infiltration and bleak prognosis." (PMID 36524115, 2022). "As a consequence, we draw a conclusion that SOX10 is a significant regulator in the glioma TME." (PMID 36524115, 2022). "Finally, we utilized single-cell sequencing to analyze the circumstances of stratification, identification, and SOX10 co-expression on glioma cells." (PMID 36524115, 2022). "Based on the large-scale machine learning, we found that the SOX family, with significant immune characteristics and genomic profiles, can be divided into two distinct clusters in gliomas, among which SOX10 was identified as an excellent immune regulator of macrophage in gliomas." (PMID 36524115, 2022). "We have found that IGF2R, INSR, and IGF1R have a tight relationship with SOX10 in gliomas." (PMID 36524115, 2022). "More importantly, our analysis of SOX10 expression files in gliomas implies its predictive ability." (PMID 36524115, 2022). "SOX10, a transcription factor that interacts with Olig2, is important in non-neoplastic oligodendroglial development, and the dys-regulation of mRNA transcripts and protein expression are identified in a wider variety of CNS glial neoplasms." (PMID 35729639, 2022). "However, some malignant gliomas and especially pediatric high-grade gliomas designated molecularly as H3.3 wt GBM_MID (or RTK1_pGBM) revealed a high degree of SOX10 nuclear expression." (PMID 33536079, 2021). "Notably, the NC specifier Sox10 has been found to be upregulated in human low-grade gliomas and a mouse model of glioma." (PMID 31569501, 2019). "We then examined whether SOX10 does indeed influence global gene expression in gliomas such as DCGs that have higher SOX10 expression." (PMID 28852847, 2017). "Furthermore, circRNA EPHB4 modulates stem properties and proliferation of gliomas via sponging miR-637 and upregulating SOX10, indicating that the RTK pathway may be involved in glioma development and progression mediated by circRNA-miRNA interactions." (PMID 38200584, 2024). "Consequently, we infer that the overexpression of SOX10 can promote glioma progression." (PMID 36524115, 2022). "On one hand, glioma programs e.g. regulated epigenetically by SETD2, SOX10, CLOCK and KDM6 instruct GAM landscapes." (PMID 40642066, 2025). "Studies in a mouse model of malignant glioma show that SOX10 is not sufficient to induce glioma tumorigenesis, likely due to the cross inhibitory relationship of SOX10 and NFIA that is present in development and is conserved during tumorigenesis in glioma." (PMID 34012965, 2021). "Circ_EPHB4 upregulates the expression of SRY-box transcription factor 10 (SOX10) and Nestin (NES) by directly sponging miR-637, thereby stimulating the stemness, proliferation, and glycolysis of glioma cells." (PMID 34829818, 2021). "SOX10 and GPR17 were primarily expressed in glioma cells from the low-edema group of patients." (PMID 39534094, 2024). "For example, in C6 glioma cells nuclear NMI was more frequent in SOX10-expressing cells compared to cells that lacked SOX10." (PMID 25174825, 2014). "In IDH-mutant/PM gliomas, coordinated hypermethylation in the transcription start site (TSS)/CpG island regions was observed in MO marker (GALC/O1), myelin components (MAG, MBP, MOBP, MOG), and essential regulators of the myelination program (MYRF/C11orf9 and SOX10)." (PMID 37055795, 2023).
glioma (continued). "Thus, the high expression of SH3KBP1 in GBM may be attributed to SOX10 high expression in GBM and the mechanisms mediating SH3KBP1 overexpression in glioma and GSCs needs further characterized." (PMID 33643898, 2020).
Hirschsprung disease (31 papers, 2012 to 2025). Hirschsprung disease (HSCR) is a congenital intestinal motility disorder that is characterized by signs of intestinal obstruction due to the presence of an aganglionic segment of variable extent in the terminal part of the colon. "The idea answer is: Coding sequence mutations in RET, GDNF, EDNRB, EDN3, and SOX10 are involved in the development of Hirschsprung disease." (PMID 40766492, 2025). "Several cases were found to have a SOX10 mutation, confirming its involvement in the Waardenburg–Hirschsprung disease." (PMID 38132479, 2023). "Two frameshift mutations within the carboxy-terminal, resulting in truncations (SOX10Dom and SOX10-59), have been associated with dominant megacolon and Waardenburg–Hirschsprung disease." (PMID 38132479, 2023). "Sox10 mutations most commonly result in Waardenburg-Shah syndrome and Hirschsprung disease, both manifesting with pigmentary abnormalities." (PMID 33803640, 2021). "SOX10 mutations have been associated with Waardenburg syndrome and Hirschsprung disease." (PMID 28107504, 2017). "In addition, variants in SOX10 may cause other neural crest-related diseases, including central demyelinating leukodystrophy, peripheral demyelinating neuropathy and Hirschsprung disease." (PMID 38659011, 2024). "Human SOX10 mutations result in Hirschsprung disease (HSCR), which is characterized by ENS reduction and intestinal dysmotility." (PMID 35143593, 2022). "Of these genes, LAMA4, ZEB2, CTNNAL1, ITGA6 and ITIH5 have previously been associated with Hirschsprung’s disease and ZEB2 was shown to genetically interact with SOX10." (PMID 39982575, 2025). "A mutation in the SRY sex determining region Y-box 10 (SOX10) gene causes WS type 2 or 4 and peripheral demyelinating neuropathy, central dysmyelinating leukodystrophy, WS, and Hirschsprung disease." (PMID 34171997, 2021). "Whereas Sox10 deletion leads to ENS developmental disorders, manifesting as Hirschsprung’s disease in humans, Sox10 overexpression in enteric neural crest stem cells or enteric progenitors cells results in the maintenance of a progenitor state and inhibition of neuronal or glial differentiation." (PMID 39982575, 2025). "Based on this discovery, SOX10 mutations were screened for in human patients with Waardenburg–Hirschsprung disease, in whom a causative mutation had not yet been identified." (PMID 38132479, 2023). "We found that zebrafish lacking an ENS due to a mutation in the Hirschsprung disease gene, sox10, develop microbiota-dependent inflammation that is transmissible between hosts." (PMID 28207737, 2017). "Mutations within the SOX10 gene are not only responsible for some WS2 cases but they also explain about 50% of WS4 cases, characterised by an association with Hirschsprung disease (HD, absence of enteric ganglia in the distal part of the intestine)." (PMID 22848661, 2012).